NNMT (nicotinamide N-methyltransferase)
Diseases named in the same sentence as NNMT in open-access papers (continued):
Sharing a sentence is not in itself a finding about the gene and the disease.
cancer (continued). "Growing evidence shows that NNMT is aberrantly expressed in and is associated with the malignancy degree of many cancers such as bladder cancer, lung cancer colorectal cancer, gastric cancer and hepatocellular carcinoma." (PMID 26942567, 2016). "Nicotinamide N-methyltransferase (NNMT) has been identified to be associated with tumorigenesis and the malignant transformation of numerous types of cancer." (PMID 25120681, 2014). "Integration with publicly available single-cell sequencing data revealed that these proteins were mostly macrophage and monocyte-associated with malignant features (TYMP, FCER1G, FCGR1A, SYK, and F13A1), except NNMT, which was highest in cancer-associated fibroblasts (Table EV4)." (PMID 41233595, 2026). "Indeed, NNMT expression is elevated in a range of human cancers and implicated in driving tumor progression." (PMID 40497995, 2025). "Additionally, NNMT is frequently overexpressed and associated with a poor prognosis in various cancers, including prostate cancer." (PMID 38254784, 2024). "Additionally, the underlying molecular mechanisms by which NNMT exerts its effects in cancer remain incompletely understood, warranting further exploration." (PMID 38809277, 2024). "NNMT plays a significant role in regulating methyl donor balance and is associated with DNA and histone methylation, involved in multiple metabolic pathways in both normal tissues and cancer cells." (PMID 37953778, 2023). "This increased expression of NNMT in cancer cells has been associated with enhanced tumorigenicity and aggressiveness, suggesting that NNMT may have a role in promoting cancer progression." (PMID 38067304, 2023). "Interestingly, in early-stage cancers, NNMT mRNA expression is significantly higher in BRAF mutated than in BRAF wild type cancers." (PMID 35177765, 2022). "Therefore, NNMT is expected to act as an effective cancer therapeutic target in BRCA1-deficient ovary tumor." (PMID 35756670, 2022). "Furthermore, lower enzyme activity leads to a higher susceptibility of cancer cells to dacarbazine, suggesting the possible involvement of NNMT in the mechanisms that underlie the development of chemoresistance." (PMID 36143291, 2022). "Moreover, NNMT has been implicated in regulating autophagy to promote cancer cell survival and maintain cancer stem cell (CSC) stemness." (PMID 35756670, 2022). "NNMT is a key regulatory molecule in the maintenance of fibroblast phenotype, and it considerably regulates most genes in the tumor stroma, thereby transforming normal fibroblasts into cancer-associated fibroblasts that support and accelerate tumor growth." (PMID 35884600, 2022). "To investigate whether tumor stromal NNMT expression is associated with clinicopathological features of the cancer patients, we analyzed various parameters, including gender, age, tumor histology, tumor differentiation, and others." (PMID 35177765, 2022). "In addition, increased expression of NNMT has been associated with tumor aggressiveness and demonstrated to facilitate the migration, invasion, viability, and proliferation of various cancer cells." (PMID 33446144, 2021). "In these neoplasms, NNMT seems to act as an interesting diagnostic biomarker, whose measurement might even be suitable for non-invasive and early cancer detection." (PMID 34439880, 2021). "In addition to being expressed in cancer cells, the presence of NNMT has been documented in metastasis-associated stroma of high grade ovarian serous carcinoma (HGSC)." (PMID 34073600, 2021). "In addition to the novel biochemistry this biosynthetic pathway offers, scleric acid has been shown to exhibit moderate antibacterial activity against M. tuberculosis, as well inhibition on the cancer-associated enzyme nicotinamide N-methyltransferase (NNMT)." (PMID 30746093, 2019).
cancer (continued). "Although several tumors have been associated with abnormal NNMT expression, its role in cancer cell metabolism remains largely unknown." (PMID 23990942, 2013). "Moreover, the development of potent and selective NNMT inhibitors could pave the way for novel therapeutic strategies targeting cancers associated with aberrant NNMT activity." (PMID 39941901, 2025). "Since the glucose metabolism is closely related with cancer drug resistance and considering the association between NNMT upregulation and the 5-FU effects on cell proliferation, NNMT may regulate 5-FU sensitivity via the Warburg effect in ESCC, promoting glucose consumption and lactate production." (PMID 34827592, 2021). "They further proved that SAH probes could enrich MT-associated proteins and be used to screen for and to assess the selectivity of MT inhibitors, which led to the discovery of a covalent inhibitor of nicotinamide N-methyltransferase (NNMT), an enzyme implicated in cancer and metabolic disorders." (PMID 28652856, 2016). "Therefore, inhibition of NNMT is considered to enhance the methylation potential and thereby may exhibit therapeutic benefits in cancers associated with insufficient histone methylation." (PMID 25120681, 2014). "Previous studies have demonstrated that Nicotinamide N-methyltransferase (NNMT) plays a crucial role in cancer metastasis and apoptosis resistance." (PMID 41816955, 2026). "Our objective was to target NNMT with novel inhibitors and determine their anti-cancer efficacy while shedding light on their possible mechanism of action." (PMID 41901361, 2026). "The enzyme, nicotinamide N-methyltransferase (NNMT), is overexpressed in a variety of human cancers, including OSCC." (PMID 41901361, 2026). "Among these downregulated genes, we noticed that a well-known anti-cancer target, Nicotinamide N-methyltransferase (NNMT), is significantly downregulated upon SNORA13 knockdown." (PMID 40529507, 2025). "Cancer stem cells, which demonstrate greater resistance to radiation than normal stem cells, often exhibit the overexpression of NNMT, which contributes to enhanced DNA repair and tumor recurrence following radiotherapy." (PMID 40725216, 2025). "Elevated NNMT expression has been consistently reported in multiple cancers, where it enhances tumorigenicity, drives epigenetic reprogramming, promotes redox imbalance, and contributes to drug resistance." (PMID 41008982, 2025). "Downstream enzymes, such as nicotinamide N-methyltransferase (NNMT), contribute to the altered epigenetic landscape in cancer cells by depleting SAM and inhibiting DNA and histone methylation." (PMID 40535116, 2025). "Recent studies have highlighted the significant role of nicotinamide N-methyltransferase (NNMT) in cancer stem cell radioresistance and its potential as a therapeutic target." (PMID 40725216, 2025). "NNMT is highly expressed in various cancer types, which subsequentially alters the epigenetic state of hypomethylated histones and various cancer-related proteins." (PMID 40529507, 2025). "More specifically, NNMT lowers the methylation potential of cancer cells by depleting SAM, which alters their epigenetic status." (PMID 40427612, 2025). "Mutations of fumarate hydratase (FH), succinate dehydrogenase (SDH), and nicotinamide N-methyltransferase (NNMT) can also lead to methylation changes in cancer cells." (PMID 40438494, 2025). "Another promising target is nicotinamide N-methyltransferase (NNMT), a metabolic enzyme overexpressed in many cancers, including MCC." (PMID 40723224, 2025). "Together, these findings underscore the importance of NNMT in cancer biology and the promise of targeted NNMT inhibitors in overcoming resistance mechanisms." (PMID 40725216, 2025). "NNMT has been identified in many preliminary studies as a good potential therapeutic target for cancers, chronic kidney disease, and metabolic disorders, such as insulin sensitivity." (PMID 38399441, 2024).
cancer (continued). "A separate study emphasized NNMT’s role in SAM depletion and reduced methylation potential as pivotal mechanisms in the regulation of cancer-associated fibroblast (CAF) differentiation." (PMID 38921477, 2024). "We employed a comprehensive pan-cancer analysis, complemented by experimental validation, to explore the potential of Nicotinamide N-methyltransferase (NNMT) as a promising therapeutic strategy for human cancers." (PMID 38809277, 2024). "Although NNMT overexpression was reported in many malignancies, the significance of its dysregulation in cancer cell phenotype was partly clarified." (PMID 38504052, 2024). "Considering its documented impact on tumor progression, clinical outcomes, and drug sensitivity, NNMT presents a promising target for drug development in various cancers with altered NNMT activity." (PMID 38921477, 2024). "The findings revealed significant overexpression of NNMT in various cancer types compared to normal tissues." (PMID 38809277, 2024). "The clinical relevance of NNMT in a range of conditions, such as cancer and metabolic disorders, has expedited the development of potent compounds targeting NNMT." (PMID 38921477, 2024). "The experimental validation of NNMT inhibition in cancer cell lines further supports its potential as a therapeutic target." (PMID 38809277, 2024). "Many studies have been carried out to elucidate the function of the NNMT in tumorigenesis and cancer cell metabolism, as well as to clarify the significance of its overexpression in different malignancies." (PMID 38504052, 2024). "The link between NNMT, epigenetic modifications, and cellular metabolism underscores its significance in cancer development and progression." (PMID 38809277, 2024). "In conclusion, our study provides compelling evidence supporting the functional significance of NNMT as a potential therapeutic target in human cancers." (PMID 38809277, 2024). "The integration of computational analysis and experimental validation in our study firmly establishes NNMT as a potential therapeutic target for human cancers." (PMID 38809277, 2024). "Inhibition of NNMT in cancer cells resulted in reduced cell proliferation and migration, further supporting its potential as a therapeutic target." (PMID 38809277, 2024). "Our results demonstrate that NNMT knockdown significantly reduces cell proliferation and migration, aligning with studies investigating NNMT’s functional consequences in various cancer types." (PMID 38809277, 2024). "The elevated expression of NNMT has been observed in diverse forms of cancer, including renal clear cell carcinoma, bladder cancer, gastric carcinoma, colorectal carcinoma, and oral squamous cell carcinoma." (PMID 38921477, 2024). "Among various potential targets, metabolic enzymes like NNMT have drawn attention because of their roles in cancer progression." (PMID 39035994, 2024). "NNMT is believed to be a critical regulator of epithelial-to-mesenchymal transition through Wnt/B-catenin signalling in cancer." (PMID 39408698, 2024). "Our results complement these findings and underscore the broader implications of NNMT dysregulation in various cancer types." (PMID 38809277, 2024). "Nicotinamide N-methyltransferase (NNMT) is a cytoplasmic protein that is increasingly accepted as a protumorigenic enzyme involved in the progression, invasion, and spread of various cancer types." (PMID 39295619, 2024). "Immunofluorescence assays indicated NNMT's subcellular localization in the cytoplasm, as it colocalized with plasmic markers in cancer cells." (PMID 38809277, 2024). "The present study offers a comprehensive examination of the functional significance of NNMT as a potential therapeutic target in human cancers." (PMID 38809277, 2024). "As NNMT has been found up- or down-regulated in different tumors, it seems to play a complex role in cancer progression and function in a tissue-specific manner." (PMID 38254798, 2024).
cancer (continued). "In light of these insights, targeting NNMT with chemical inhibitors is receiving increasing attention in cancer therapy." (PMID 38396769, 2024). "To confirm the malignant functions of NNMT in tumor cells, we conducted a series of cell-based experiments, revealing that NNMT promotes cancer cell proliferation and invasion, indicative of its oncogenic properties." (PMID 38809277, 2024). "Although different kind of cancers have been correlated with NNMT dysregulation, its role in cancer cell metabolism remains partly undiscovered." (PMID 38504052, 2024). "NNMT has been emerging as a promising therapeutic target in cancer treatment, and several NNMT inhibitors are under study for the therapeutic management of the disease." (PMID 38790711, 2024). "NNMT is a potential target for cancer therapy development; there are currently three main types of NNMT inhibitors: competitive, bi-substrate, and covalent." (PMID 39272943, 2024). "Accumulating evidence has shown that a knockdown of NNMT reduces both tumorigenesis and chemoresistance and further research is needed to explore NNMT’s potential as a therapeutic target for improving anti-cancer treatments." (PMID 39272943, 2024). "Collectively, these findings indicate that NNMT expression is elevated in various cancers, and that its downregulation can normalize the stroma and diminish the metastatic and invasive capabilities of cancer cells." (PMID 38921477, 2024). "Because of this, NNMT expression is responsible for controlling the methylation potential of cancer cells." (PMID 37889548, 2023). "In the context of cancer, NNMT has been found to be overexpressed in various solid tumors, including OSCC." (PMID 38067304, 2023). "First, we evaluated the NNMT mRNA levels in diverse cancers and their matched adjacent normal tissues over a cancer-wide range in Oncomine and TIMER databases." (PMID 36817086, 2023). "NNMT is largely studied in cancer, where it was found to be upregulated in several types of solid tumors." (PMID 36829935, 2023). "NNMT protein levels in 2 cancer cell line panels, the CCLE and NCI60, correlated strongly to NNMT expression (respectively)." (PMID 37883365, 2023). "Compared with these studies, our results showed that NNMT expression level had a positively correlations with infiltration levels of CAFs in 30 types of cancer." (PMID 36817086, 2023). "Combined with the previous research, our results serve as a reminder that NNMT regulates the CAFs in various cancers." (PMID 36817086, 2023). "In summary, we demonstrated that NNMT expression was related to clinicopathological characteristics and poor prognosis of pan-cancer." (PMID 36817086, 2023). "We recently discovered that NNMT is significantly more expressed in EC than in other cancers and plays a significant role in the metastasis and survival of EC patients using this extensive patient observation data and public datasets (TCGA)." (PMID 37889548, 2023). "NNMT was significantly up-regulated in tumour samples compared to matched normal samples in 3/12 cancer types, with 4/12 showing significant down-regulation." (PMID 37883365, 2023). "In comparison, NNMT expression and its ratio to that in normal tissues in ccRCC patients were among the highest across many cancers." (PMID 36750850, 2023). "The depletion of SAM has been observed in several cancers due to overexpression of the enzyme Nicotinamide N-methyltransferase (NNMT)." (PMID 36672415, 2023). "It has been revealed that NNMT is a prognostic marker for several malignancies and promotes cell proliferation in many forms of cancer." (PMID 37889548, 2023). "The study of lysine histone methyltransferase (KMT) and nicotinamide N-methyltransferase (NNMT) inhibitors is important for understanding cancer epigenetic mechanisms and biological processes." (PMID 38136297, 2023).
cancer (continued). "Again, the combined treatment was able to affect cancer resistance by reducing NNMT expression at both the mRNA and protein levels as a result of the downregulation of p-STAT3, a well-known upstream regulator of NNMT." (PMID 37628772, 2023). "For example, in cancer, NNMT is highly expressed, which is thought to facilitate dysfunctional metabolism leading to tumor growth." (PMID 36984839, 2023). "Several reports have addressed NNMT’s involvement in lipid metabolism in non-cancer settings, though the issue remains controversial." (PMID 36750850, 2023). "By restoring NAD+ levels and modulating epigenetic processes, NNMT inhibitors have the potential to restore normal gene expression patterns and counteract the aberrant epigenetic changes observed in cancer cells." (PMID 38067304, 2023). "For the same reason, the use of NNMT inhibitors, widely studied for anti-cancer applications, should be carefully evaluated in order to prevent negative effects consequent to SIRT1 inhibition." (PMID 36829935, 2023). "Evidence that NNMT plays an important role in cancer can be seen by the fact that NNMT knockdown reduces tumorigenesis and chemoresistance and that Yuanhuadine, a natural inhibitor of NNM, reverses EGFR inhibitors ADR." (PMID 36902166, 2023). "Out of these, and based on the available literature data about their involvement in cancer and BCa, and positive correlation with stage, we have preselected NNMT, GALK1, and HTRA1 to be further tested in urine samples." (PMID 37834386, 2023). "Emerging evidence has revealed the significant roles of nicotinamide n-methyltransferase (NNMT) in cancer initiation, development, and progression; however, a pan-cancer analysis of NNMT has not been conducted." (PMID 36817086, 2023). "High NNMT expression has been implicated in SAM depletion in embryonic stem cells and cancer-associated fibroblasts (CAFs)." (PMID 35119359, 2022). "NNMT over expressing cancer cells that have grown in 20 μM methionine had a more dramatic reduction of SAM levels than those that have grown in 100 μM methionine." (PMID 35756670, 2022). "In summary, we identified NNMT as a host factor that mediates cancer-induced rewiring of nitrogen homeostasis in the liver." (PMID 35705545, 2022). "Second, the identification of host factors involved in NNMT-independent phenomena will be critical to establish therapeutics that efficiently ameliorate cancer’s adverse effects on the host." (PMID 35705545, 2022). "With the development of more studies and clinical trials, we strongly believe that NNMT inhibitors can confer considerable benefit on patients with cancer." (PMID 35756670, 2022). "NNMT expression is extremely low in OXPHOS‐sensitive cancer cells with its gene promoter region highly methylated." (PMID 36382559, 2022). "In mesenchymal cancer stem cells, NNMT overexpression depleted intracellular NAM and therefore enhanced the activity of PARP1, increasing the chemoradiotherapy resistance of cancer cells." (PMID 35338115, 2022). "NNMT is also involved in regulating autophagy to maintain cancer cell survival via the mTOR and AMPK pathways." (PMID 35756670, 2022). "Consistent with this, data from the transfection assay portion of one study showed that NNMT activity promoted cancer cell migration and invasion." (PMID 36291696, 2022). "Consistently, the NNMT expression level is significantly decreased in the sensitive cancer cells in concomitance with the precipitously increased DNA methylation in its promoter region." (PMID 36382559, 2022). "As we have summarized, preliminary studies have shown that NNMT plays a key role in various cancers and is expected to be a novel therapeutic antitumor target." (PMID 35756670, 2022). "In the current study, we combined mouse genetics and multi-omics analyses to demonstrate that host NNMT is involved in cancer-induced metabolic dysfunctions within the liver." (PMID 35705545, 2022).